MET (MET proto-oncogene, receptor tyrosine kinase)
Diseases named in the same sentence as MET in open-access papers (continued):
Sharing a sentence is not in itself a finding about the gene and the disease.
osteosarcoma (continued). "Another immunohistochemical study found that plasma membrane and cytoplasmic staining for MET/HGF receptor were positive in 71% of osteosarcoma cases." (PMID 38596618, 2024). "Another study showed that all osteosarcoma cell lines had elevated MET expression in the cDNA array." (PMID 38596618, 2024). "The role of the MET oncogene product between primary and metastatic sites in osteosarcoma has remained controversial." (PMID 38596618, 2024). "N-methyl-N′-nitroso-guanidine human osteosarcoma transforming gene, often referred to as MET, is a tyrosine kinase." (PMID 39458991, 2024). "Immunohistochemical analysis revealed MET overexpression in primary (95%), local recurrences (100%), and metastases (82%) of osteosarcomas." (PMID 38596618, 2024). "Cabozantinib, a TKI targeting VEGFR2 and MET (a transmembrane tyrosine kinase receptor), decreased the proliferation and migration of osteosarcoma cells, and the production of RANK ligands via inhibition of the ERK and AKT signaling pathways." (PMID 37377920, 2023). "The proportion of patients with drug resistance due to N-methyl-N′-nitroso-guanidine human osteosarcoma transforming gene (MET) amplification is 5% to 9%." (PMID 37789988, 2023). "In osteosarcoma cell lines, including D-17, siRNA or drug-induced MET inhibition resulted in decreased motility and invasiveness." (PMID 37048099, 2023). "PVT1 activated the PI3K/AKT pathway via c-MET to increase the chemotherapy resistance of osteosarcoma cells." (PMID 37580768, 2023). "PVT1 had a pivotal role in the GEM resistance of osteosarcoma cells through miR-152 targeting to regulate the c-MET/PI3K pathway." (PMID 37580768, 2023). "Cabozantinib is an inhibitor of VEGFR2 and MET and was studied in 43 osteosarcoma patients, of which 39 had pulmonary metastases, in a phase II clinical trial." (PMID 35409176, 2022). "Our recent study has shown that LCN2 suppresses MET expression to inhibit osteosarcoma cell metastasis." (PMID 36428800, 2022). "Overall, the HGF/c- MET pathway is an exciting target and has shown early promise in cancers such as osteosarcoma." (PMID 36034555, 2022). "Among them, MET is the most significantly upregulated gene in LCN2-knockdown cells and there are some reports regarding MET and osteosarcoma metastasis." (PMID 34202288, 2021). "The inhibition of c-MET with crizotinib induced significant reduction in the malignant potential of osteosarcoma cells in in vivo and in vitro models." (PMID 34069999, 2021). "A Phase II study of cabozantinib (which targets VEGFR-2, the AXL receptor tyrosine kinase, and c-MET) in 42 patients with heavily pretreated, advanced osteosarcoma reported a median PFS of 6.2 months." (PMID 34117970, 2021). "The inhibition of miR-489-3p contributes to the metastasis of osteosarcoma via regulating PAX3/MET signaling." (PMID 34177591, 2021). "Among patients with osteosarcoma, a low VEGF-A concentration (<12.5 pg/mL) was associated with a better OS (13.2 vs. 8.2 months, p = 0.014) while high soluble MET levels (>300.6 ng/mL) were associated with a better PFS (7.8 vs. 5.4 months, p = 0.016)." (PMID 34069999, 2021). "Sun et al24 demonstrated that lncRNA PVT1 is involved in the resistance of osteosarcoma cells through activation of the c‐MET/PI3K/AKT pathway." (PMID 32960485, 2021). "The overexpression of MET, a target gene for both miRNAs, is present in 70%–80% of human osteosarcomas and contributes to an aggressive phenotype." (PMID 33008041, 2020). "LncRNA PVT1 targets miR-152 and enhances the resistance of osteosarcoma to gemcitabine by activating the c-MET/PI3K/AKT pathway." (PMID 32202509, 2020). "Lower levels of miR-1 and miR-133b in canine osteosarcoma tissues were found to increase tumorigenesis through a higher expression of their target genes MET and MCL1." (PMID 33008041, 2020).
osteosarcoma (continued). "Cabozantinib is a VEGFR2 tyrosine kinase inhibitor that is also able to inhibit MET, the protein product of the TPR-MET transforming oncogene derived from an osteosarcoma cell line." (PMID 32961800, 2020). "Other studies also found that inhibiting the MET signaling pathway can increase apoptotic rate and suppress the migration, proliferation, and invasion of osteosarcoma cells." (PMID 32984034, 2020). "LncPVT1 can promote gemcitabine resistance in osteosarcoma by serving as a ceRNA of miR-152 and disinhibiting c-MET and the downstream PI3K/AKT pathway." (PMID 31508377, 2019). "Previous studies have shown that c-MET mediates chemoresistance to cisplatin in osteosarcoma and that miR-152 acts as a tumor suppressor by targeting c-MET in oral squamous cell carcinoma." (PMID 31508377, 2019). "MET is overexpressed in osteosarcoma tissues and facilitates osteosarcoma cell proliferation, migration, and invasion." (PMID 31645479, 2019). "MET was originally identified from a chemically transformed human osteosarcoma cell line as an oncogene resulting from the chromosomal rearrangement of the MET tyrosine kinase domain with a dimerization domain (TRP-MET)." (PMID 30544501, 2018). "Compared to vehicle treatment, miR-34a led to a 40% suppression of c-MET protein levels, a well-defined miR-34a target being involved in osteosarcoma metastasis." (PMID 28415566, 2017). "Some of these genes, or the pathways they regulate, including the PVT1/MYC locus, MET signaling, and IGF1R have been implicated in genetically engineered mouse models of osteosarcoma." (PMID 29056713, 2016). "Originally, MET was identified as an oncogene that promotes anchorage-independent growth of osteosarcoma cells in soft agar." (PMID 23296269, 2013). "The western blotting results showed that over-expression of miR-133b decreased the expression of BCL2L2, MCL-1, IGF1R and MET in osteosarcoma cells U2-OS and MG-63." (PMID 24391788, 2013). "MET overexpression has been identified in numerous human tumours, and its tumorigenic properties have recently been demonstrated in osteosarcomas, where it is able to drive the transformation of osteoblasts into malignant cells." (PMID 22736953, 2012). "Activation of c-MET/HGF in osteosarcomas may contribute to downstream signaling pathways involved with motility, mitogenesis, and morphogenesis in an aggressive manner." (PMID 40361420, 2025). "Our experimental results demonstrate that the combined use of MET inhibitors in osteosarcoma may be a strategy to enhance the killing effect of Anlotinib." (PMID 39605750, 2024). "The consistent detection of MET proto-oncogene overexpression in both primary and recurrent lesions, as well as in the majority of metastases, is significant for understanding the pathogenesis of osteosarcoma." (PMID 38596618, 2024). "Since osteosarcomas are histologically characterized by malignant osteoblasts producing an osteoid component, this research team examined the genomic status of MET, TWIST, and APC genes involved in ossification processes in pediatric osteosarcomas treated with the OS94 protocol." (PMID 38596618, 2024). "Moreover, crizotinib effectively suppressed migration and invasion of osteosarcoma cells while decreasing the expression of MET/Gab1/STAT5." (PMID 38596618, 2024). "Osteosarcoma cell glycolysis, proliferation, migration and invasion were suppressed by decreasing glycolysis-related proteins and migration-related proteins via the inhibition of c-MET and AKT3/mTOR." (PMID 38396845, 2024). "Several studies have confirmed the expression of ERBB2 and MET in human and canine osteosarcoma." (PMID 37048099, 2023). "While MET expression did not correlate with overall survival time or disease-free survival time in canine osteosarcoma patients, a significant association with a lymphogenic route of metastasis was observed." (PMID 37048099, 2023). "miR-152 attenuated lncRNA PVT1-induced apoptosis via c-MET/PI3K/AKT pathway in osteosarcoma cell." (PMID 36445489, 2023).
osteosarcoma (continued). "This oncogene was first identified in a human osteosarcoma cell line containing the transforming fusion protein TPR–MET, generated by a rearrangement between a translocation promoter region (TPR) located on chromosome 1 at the 5’ end and the MET gene located on chromosome 7 at the 3’ end." (PMID 36499382, 2022). "Hence, we confirmed the novel discovery that illustrated the anti-metastatic property of LCNS involving the MEK–ERK pathway and downstream MET in human osteosarcoma." (PMID 34202288, 2021). "Moreover, c-MET is overexpressed in osteoblasts, contributing to their transformation into osteosarcoma cells." (PMID 34069999, 2021). "In addition, c-MET plays an essential role in miR-152-regulated PI3K/AKT signaling in osteosarcoma cells." (PMID 32194780, 2020). "MET overexpression has been demonstrated to convert primary human osteoblasts into osteosarcoma." (PMID 26510912, 2015). "In addition, over-expression of miR-1 and miR-133b inhibits osteosarcoma cell proliferation and invasion through cell cycle arrest and decreasing MET expression." (PMID 24391788, 2013). "These suggested that MET may co-cause disease progression with VEGFR2 in osteosarcoma.To verify whether MET is a factor contributing to Anlotinib resistance in osteosarcomacells, this study selected four osteosarcoma cell lines: U2OS, DuNN, SaOS-2, and HOS." (PMID 39605750, 2024). "However, the multi-target MET inhibitor cabozantinib has a high efficiency in osteosarcoma." (PMID 32984034, 2020). "In 12 osteosarcoma cell lines, the MET/HGF receptor exhibited overexpression, phosphorylation upon HGF stimulation, and full functionality." (PMID 38596618, 2024). "Although anlotinib can significantly inhibit the growth of osteosarcoma cells and xenografts by suppressing VEGFR2 and MET phosphorylation, the prognosis of advanced osteosarcoma patients treated with anlotinib remains controversial." (PMID 39618078, 2024). "This new discovery illustrates the involvement of the MEK–ERK pathway and downstream MET on migration of osteosarcoma, which in turn illustrates the pertinence of further studying LCN2 related to anti-metastasis for human osteosarcoma." (PMID 34202288, 2021). "In the same study, osteosarcoma‐derived MNNG/HOS cells were shown to be dependent on MET signaling and sensitive to MET inhibitors." (PMID 30979792, 2019). "The function of miR-199a-3p and miR-34a in cell proliferation and apoptosis, it was clearly dependent on the presence of mTOR, MET and MDM4 gene in human osteosarcoma cells." (PMID 24957404, 2014). "Over-expression of miR-133b in osteosarcoma cell lines U2-OS and MG-63 decreases the expression of BCL2L2, MCL-1, IGF1R, MET and FAK, leading to the inactivation of Akt." (PMID 24391788, 2013). "These indicate that miR-133b play a role as a tumor suppressor gene in osteosarcoma through inhibiting PI3K/Akt signaling and down-regulating several anti-apoptotic molecules and oncogenes such as BCL2L2, MCL-1, IGF1R, MET, and FAK." (PMID 24391788, 2013). "Over-expression of miR-133b in osteosarcoma cell lines U2-OS and MG-63 led to the inhibition of cell proliferation, migration, invasion through decreasing the expression of IGF1R, MET, phospho-Akt and FAK." (PMID 24391788, 2013). "Further, to better understand the mechanisms how miR-133b regulates cellular phenotypes of osteosarcoma cells, we first measured the expression of BCL2L2, MCL-1, IGF1R and MET, which are identified as the target genes of miR-133b in several cancers." (PMID 24391788, 2013). "Results showed that expression of BCL2L2, MCL-1, IGF1R, MET, phospho-Akt and FAK were significantly decreased in miR-133b over-expressed osteosarcoma cell lines U2-OS and MG-63." (PMID 24391788, 2013). "MET was first cloned as a transforming gene from a chemically transformed osteosarcoma cell line, later HGF was identified as the only known ligand for c-Met." (PMID 19187270, 2009).
osteosarcoma (continued). "MET, a receptor tyrosine kinase proto-oncogene and the specific receptor for hepatocyte growth factor (HGF), plays a critical role in the initiation and progression of osteosarcoma (OS) through sustained pathway activation." (PMID 40599602, 2025). "Initially identified as a product of chromosomal rearrangement induced by carcinogens in the human osteosarcoma cell line HOS, MET was formed through fusion between the translocated promoter region (TPR) locus on chromosome one and the MET sequence on chromosome 7." (PMID 38596618, 2024). "The results demonstrated significant staining of MET and HGF/SF in osteosarcomas." (PMID 38596618, 2024). "In recent years, several studies have assessed the expression of MET and HGF in osteosarcoma." (PMID 38596618, 2024). "In a limited number of previous studies, it was confirmed that anlotinib suppressed osteosarcoma growth and metastasis via dual blockade of VEGFR2 and MET, and anlotinib was also found to reverse multidrug resistance (MDR) in osteosarcoma by inhibiting p-glycoprotein (PGP1) function." (PMID 38381883, 2024). "In a chemically transformed human osteosarcoma-derived cell line, the N-terminal sequence of TPR was found to be fused to the kinase domain of the proto-oncogene MET, leading to the constitutive activation of MET." (PMID 34793452, 2021). "In particular, expressions of MET/HGF receptor in osteosarcoma with and without bone metastasis were noted in 25 and 90% of cases, respectively." (PMID 34202288, 2021). "The receptors MET, IGF-1R, AXL, PDGFRs, KIT, and FGFRs might be relevant but unimportant RTKs for osteosarcoma." (PMID 32984034, 2020). "In osteosarcoma cell lines (MG-63 and U-2OS), EGCG induced miRNA-1 upregulation and inhibited c-MET expression, while its combination with c-MET inhibitor enhanced inhibitory effects on tumor cell growth, heading to cell proliferation reduction, cell cycle arrest, and apoptosis induction." (PMID 31979082, 2020). "The receptor tyrosine kinases (RTKs) MET, IGF-1R, AXL, PDGFRs, KIT, and FGFRs might be relevant but unimportant targets for osteosarcoma treatment." (PMID 32984034, 2020). "Tumors of mesenchymal origin, such as osteosarcomas and rhabdomyosarcomas that physiologically express HGF, can acquire an aberrant expression of MET leading to the establishment of an autocrine loop that sustains constitutive activation of the signaling pathway." (PMID 30544501, 2018). "Our research demonstrated that miR-199a-3p and miR-34a could down-regulate its target genes, mTOR, MET and MDM4 in human osteosarcoma cells." (PMID 24957404, 2014). "Furthermore, a review of the literature suggests that KIT, PDGFRs, MET, IGF‐1R, and AXL could also serve as potential therapeutic targets for osteosarcoma." (PMID 40344484, 2025). "IGFBP5 has been identified as a hub gene in osteosarcoma along with origin recognition complex subunit 6 (ORC6), minichromosome maintenance 10 replication initiation factor (MCM10), MET proto-oncogene, receptor tyrosine kinase (MET) and centromere protein F (CENPF)." (PMID 36465383, 2022). "There is no report about the treatment of osteosarcoma with a selective MET inhibitor." (PMID 32984034, 2020). "In addition, we reviewed the literature and found that MET, IGF-1R, and AXL may also be relevant targets for the treatment of osteosarcoma." (PMID 32984034, 2020).
renal cell carcinoma (90 papers, 2012 to 2025). "Overexpression of c-MET is associated with poor prognosis in several types of cancer, including renal cell carcinoma (RCC)." (PMID 39325320, 2024). "MET mutation drives oncogene amplification and overexpression, which have been implicated in a variety of human cancers such as renal cell carcinoma." (PMID 36713541, 2022). "For instance, mutations such as Y1248C and M1268I occur in the proto-oncogene MET and are associated with poor prognosis in renal cell carcinoma." (PMID 34068918, 2021). "We have examined MET expression, frequency of MET gene copy gains and MET gene mutation in a large, hospital-based series of renal cell carcinomas with long-term follow-up information." (PMID 27894094, 2017). "Targets of Hsa-miR-200b-3p were involved in several pathways like renal cell carcinoma, associated to some oncogenes such as MET, or tumors suppressors like VHL, FH and BHD." (PMID 23372853, 2013). "Familial renal cell carcinoma (RCC) is reported with mutations in MET protooncogene at 7q31.1–34 in the papillary RCC type." (PMID 27087812, 2016). "Mutation of the MET gene is thought to be a rare event in cancer, but it is often found in papillary renal cell carcinoma (RCC) and childhood hepatocellular carcinoma." (PMID 25521854, 2014). "In a separate study, it is found that lncARSR facilitates the expression of AXL and c-MET by competitively binding miR-34/miR-449, thereby enhancing resistance to sunitinib in renal cell carcinoma cells." (PMID 38100482, 2023). "According to CTRP drug sensitivity analysis, high level of CBX2, BLNK, PLK4, STIL and BIRC5 were associated with increased sensitivity to inhibitors of VEGF and MET pathways, which happened to be two crucial driver pathways of renal cell carcinoma." (PMID 37917664, 2023). "Two MET inhibitors, crizotinib and cabozantinib, are FDA approved for NSCLC and renal cell carcinoma, respectively, and a wide variety of other MET inhibitors are in clinical trials." (PMID 36530465, 2022). "MiT family translocation renal cell carcinoma (TRCC) is a rare and aggressive subgroup of renal cell carcinoma harboring high expression of c-MET." (PMID 35979929, 2022). "Upregulation of the receptor tyrosin kinase c-MET in renal cell carcinoma (RCC) is correlated with overall survival in metastatic disease (mRCC)." (PMID 34708249, 2022). "A 57-year female suffering from renal cell cancer with moderately MET-amplified tumors (7.5 copies, MET/CEP7 ratio of 2.7) was treated in the SE cohort at 3 mg/kg Q2W." (PMID 34200749, 2021). "Co-expression of matriptase and MET was also reported to correlate with poor prognosis in head and neck cancer, and renal cell carcinoma." (PMID 30469509, 2018). "In the METEOR trial, 658 patients with advanced renal cell carcinoma who progressed with at least one VEGFR small molecule inhibitor were randomized to the MET inhibitor cabozantinib or the mTOR inhibitor everolimus." (PMID 29866143, 2018). "In this study, we employed a mouse model of renal cell carcinoma (RCC) bone metastasis to clarify the significance of the HGF/MET signaling axis and the regulator of HGF activator inhibitor type-2 (HAI-2)." (PMID 29890660, 2018). "Of interest in this regard, MET is prominently expressed (as determined by immunohistochemistry) at the site of bone metastases in renal cell cancer." (PMID 29866143, 2018). "The MET/hepatocyte growth factor (HGF) pathway is a potential candidate, since MET-induced signaling has been reported to induce PD-L1 expression in renal cell cancers." (PMID 29137273, 2017). "Investigation of rare familial forms of renal cell carcinoma (RCC) has led to the identification of genes such as VHL and MET that are also implicated in the pathogenesis of sporadic RCC." (PMID 24000165, 2013).